MIR1302-10 (microRNA 1302-10)
Synonyms: hsa-mir-1302-10
Gene: MicroRNA gene on chromosome 15 (101,960,459 to 101,960,596, reverse strand). Ensembl gene ENSG00000284557.
Gene Ontology:
Biological process: miRNA-mediated post-transcriptional gene silencing
Homologues: Paralogues in human: MIR1302-11 (100% identical), MIR1302-2 (100% identical), MIR1302-9 (100% identical).